CD4 (CD4 molecule)
Diseases named in the same sentence as CD4 in open-access papers (continued):
Sharing a sentence is not in itself a finding about the gene and the disease.
HCMV infection (continued). "Owing to the strong association of CD4+CD28null T cells to HCMV seropositivity, it is tempting to assume that the location or status of the HCMV infection plays an important role." (PMID 17825098, 2007). "Moreover, it has been shown that during HCMV infection, HLA-DR+ NK cells are able to present viral antigens to CD4+ T cells and promote the development of an adaptive response." (PMID 38276503, 2024). "CD4+ T cells expressing CD25 and FOXP3 (TREGs), producing IL10, an immunosuppressive cytokine, have also been observed and are implicated in immune suppression in CMV infection and reactivation." (PMID 38501302, 2024). "Preexisting antibodies were observed to protect against CMV infection in monkeys, while a depletion of CD4+ cells could lead to an increase in viral transmission." (PMID 38303144, 2024). "CD4 effector T cells in HCMV infections act via both cytokine-dependent and cytolytic mechanisms." (PMID 36445084, 2022). "Future mechanistic studies in the context of HSCT and HCMV infection (perhaps in animal models where such CD4+ T cells can be manipulated) will be an important component of work to determine the role of these cells in the context of preventing high level viraemia." (PMID 35546552, 2022). "As pUL11 perturbs CD4 T cell function and induces IL-10, which can directly limit CD4 T cell activation and expansion, we investigated whether the presence of pUL11 can influence CD4 T cell control of an HCMV infection." (PMID 36445084, 2022). "Therefore, the presence of pUL11 inhibits CD4 T cell control of HCMV infections in epithelial cells." (PMID 36445084, 2022). "Notably, increased LD CD4+ T cells are one of the features of senescence, which is involved in multiple diseases, especially cytomegalovirus infection." (PMID 35608657, 2022). "Since HCMV reactivation in the TME could lead to increased IL-6 production, these data suggest that active HCMV infection in the TME may also drive the expansion of highly suppressive CD4+TNFR2+ Tregs." (PMID 33808294, 2021). "Intriguingly, HCMV infection is a major trigger of CD4+CD28− T-cells expansion." (PMID 33567734, 2021). "After a primary maternal hCMV infection in the first trimester, hyperimmunoglobulin administration apparently prevents maternal–fetal transmission, implicitly suggesting a role of antibodies, and CD4+ T cells have been correlated with protection against hCMV." (PMID 34070277, 2021). "Our workflow allows the efficient determination of events featuring HCMV infection such as CD4/CD8 ratio, CD8 inflation and differentiation, HCMV peptide-specific HLA-EUL40 and HLA-A2pp65CD8 T cells, and expansion of γδT and NK subsets including δ2−γT and memory-like NKG2C+CD57+ NK cells." (PMID 35008688, 2021). "Studies of the role of CMV-specific CD4+ T cells during acute CMV infection in healthy adults have mainly been conducted in pregnant women cohorts, these have revealed that at early time points post infection responses to gB and pp65 CMV proteins are the dominant responses." (PMID 32509591, 2020). "A large Swedish study of infants up to 2 years of age with congenital CMV infection found that they had CMV-specific CD4+ T cell responses (measured by IFN-γ) that were inferior compared to adults during the first 3 months of age, though this difference was not significant by the age of 24 months." (PMID 32509591, 2020). "However, as already discussed it is clear that in the case of HCMV infection CD4+ T cells are a necessary component of CMV T cell therapy." (PMID 32509591, 2020). "A study involving 38 SOT CMV sero-positive recipients showed that patients with a higher number of HCMV-specific CD4+ T cells detected prior to transplantation were more likely to have earlier immune restoration and less likely to have HCMV infections requiring anti-viral treatment." (PMID 32509591, 2020).
HCMV infection (continued). "HCMV infection is known to cause a massive clonal expansion of the CD8+ T cell population in adults and children, and a lesser but still considerable expansion of CD4+ T cells in both adults and children leading to inversion of the normal CD4:CD8 ratio to <1." (PMID 32582177, 2020). "Finally, in HCMV infection, up to 30% of all circulating CD4-positive T lymphocytes become the primary target of the virus in infected elderly individuals." (PMID 32825448, 2020). "Besides the HCMV infection profile, they additionally demonstrated human CD4+ and CD8+ T cell responses against the viral IE1 and pp65 proteins." (PMID 32079250, 2020). "HDAC1cKO-HDAC2HET mice induce CD4+ CTL features in Th cells upon murine cytomegalovirus infection." (PMID 32102981, 2020). "An additional open question is where antigen presentation by NK cells to specific effector memory CD4+ T cells may take place and to what extent this mechanism could contribute to HCMV infection control." (PMID 31001281, 2019). "Although no direct evidence of an association of CD28null CD4 T cells with MS severity was found in humans, the authors observed expansion of CD28null CD4 T cells in response to CMV infection in a mouse CMV (MCMV) model." (PMID 30984377, 2019). "Taken together this suggests that latent HCMV infection manipulates the immune response towards a more suppressive phenotype, which is in contrast to the predominantly anti-viral effector phenotype of CD4 + T cells specific to HCMV proteins expressed during lytic infection such as pp65,IE and gB." (PMID 30895366, 2019). "Our model was conceived to illustrate one possible way how CMV infection might worsen the clinical course of RA via CD28null CD4 T cells." (PMID 30984377, 2019). "At this time, it remains unclear, which signals drive the expression of Hobit in cytotoxic CD4+ T cells after hCMV infection." (PMID 28392788, 2017). "In humans, this cytotoxic profile is found within the human cytomegalovirus (hCMV)-specific, but not within the influenza- or Epstein–Barr virus-specific CD4+ T cell populations, suggesting that, in particular, hCMV infection induces the formation of cytotoxic CD4+ T cells." (PMID 28392788, 2017). "Interestingly, γδ+ T cells that arise after hCMV infection also upregulate Hobit expression and display a similar effector phenotype as cytotoxic CD4+ and CD8+ T cells." (PMID 28392788, 2017). "Interestingly, AAV patients with a previous CMV infection had a significantly higher percentage of CD4+CD28null T cells than HC with a previous CMV infection." (PMID 28084533, 2017). "During CMV infection, CD4+ and CD8+ T cell responses either follow the traditional course comprised by massive expansion followed by rapid contraction and maintenance at low levels or instead do not undergo contraction but remain at high frequency or even expand gradually." (PMID 28265272, 2017). "In addition, we identified that presence of the anti-inflammatory cytokine IL-10, secreted by APCs and other cells during the early phase of mouse CMV infection, leads to suppression of CD4 T cell priming." (PMID 23717308, 2013). "We have recently shown that early induction of cellular IL-10 during acute mouse CMV infection leads to impaired NK/DC cross-talk and suppression of CD4 T cell priming affecting CD4 T cell proliferation and cytokine secretion, thus shifting the virus/host balance and promoting virus-persistence." (PMID 23717308, 2013). "Furthermore, the presence of CD4+ CD25+ cells was shown to suppress the function of antiviral CD8 T cells upon HCMV infection in vitro in an antigen-independent manner." (PMID 23717308, 2013). "Conversely, some authors indicate that HCMV-specific CD4+ T-cells may be sufficient to predict a reliable control of HCMV infection." (PMID 22848556, 2012).
HCMV infection (continued). "In addition, recent research has reported that cytotoxic CD4+ T cells eliminate senescent fibroblasts in human skin by targeting cytomegalovirus antigens, further highlighting the importance of T cell immunity for HCMV infection." (PMID 38829126, 2024). "Notably, CD4 + T-cells have been found to be essential for controlling HCMV infection." (PMID 37376633, 2023). "A number of studies using such transplant patients as model for primary HCMV infection—as the time of infection can be determined post-transplant surgery—have been undertaken, which has allowed the kinetics of the developing immune response for both CD4+ and CD8+ T cells to be assessed." (PMID 36558866, 2022). "As previously discussed, HCMV infection modulates the hosts IL-10 pathway, both directly through expression of viral-encoded IL-10 homologs and indirectly by altering the secretome of the infected cell, in addition to generating cellular IL-10-secreting CMV-specific CD4+ T cells." (PMID 28647908, 2017). "Additionally, memory inflation in latent HCMV infection may also impact the balance between Th1 and Th2 cytokine production by CD4+ T cells in aged individuals, shifting it in favor of Th1 responses." (PMID 28082969, 2016). "Furthermore, adoptive T-cell immunotherapy interventions showed that maintenance of HCMV-specific CD8+ T-cells infused after bone marrow transplantation required the presence of HCMV-specific CD4+ T-cells, further suggesting a critical role for CD4+ T-cells during HCMV infection." (PMID 25166270, 2014). "Increased frequencies of circulating CD4+CD28null T cells in patients with RA have been associated with HCMV infection; whether this is also valid for synovial CD4+CD28null T cells is not known." (PMID 17825098, 2007). "CD4+CD28null T cells and HCMV might not be the only mediators of cardiovascular events in RA, but these studies together strongly link CD4+CD28null T cells and HCMV infection to cardiovascular events, which is found with increased prevalence and is the major cause of death in patients with RA." (PMID 17825098, 2007). "In accordance with the relevance of CD4 + T cells and CIITA-driven HLA-II presentation, BLS patients frequently suffer from severe, persistent HCMV infections." (PMID 40608405, 2025). "For example, γδ T cells not only process endogenous antigens to induce activation of CD4+ αβ T cells but also uptake and cross-present soluble antigens to activate CD8+ αβ T cells in HCMV infections." (PMID 40245023, 2025). "T cells and B cells also play important roles in HCMV infection, as CD4+ and CD8+ T cells regulate the balance between persistent and latent HCMV infection." (PMID 41362154, 2025). "Cytomegalovirus infection increased CD3 + CD8 + midCD56+ NK‐T cells and CD3 + CD8+ T cells, while BK polyomavirus reactivation decreased CD4+ and CD8+ T cells." (PMID 41321698, 2025). "We confirmed that V160 de novo induces potent IE-1 and pp65 specific polyfunctional CD4 T and CD8 T cell responses, which are similar to those induced by natural HCMV infection." (PMID 38561339, 2024). "This study utilized recently developed mAb treatments to study the roles of CD4+ and CD8+ T cells in the immune response to primary CMV infection." (PMID 39495799, 2024). "This study investigated the role of CD4+ and CD8+ T cells in a guinea pig model of primary cytomegalovirus infection." (PMID 39495799, 2024). "To investigate the immunomodulatory effects of treatment with Tα1 + PCDs in CD4+ and CD8+ T cells during HCMV infection, we evaluated the expression of CD2 and CD40L, as well as the production of TNFα, IFNγ and IL-2 using multiparametric cytometry." (PMID 38396631, 2024). "Considering that the emergence of the hCMV-specific CD4+ T cells precedes that of CD8+ T cells, they were mostly thought to perform supportive roles by enhancing the CD8+ T cell responses to the hCMV infection." (PMID 38501302, 2024).
HCMV infection (continued). "Modulation of the MHC II-mediated cellular immune response has been also described for human cytomegalovirus infection, where the viral protein pUS2 destroys HLA-DMA and -DRA to prevent recognition by CD4 + T cells." (PMID 37604847, 2023). "CD4+ T cells are more abundant than CD8+ T cells in most HCMV-seronegative healthy adults, whereas HCMV infection commonly inverts this ratio." (PMID 37234158, 2023). "A lack of differences in surrogate markers of T cell function led us to investigate direct effector functions of CD4+ and CD8+ T cells in response to HCMV infection." (PMID 36591233, 2022). "In recent years, many studies have shown that PD-1 expression on the surface of CD4+ and CD8+ T cells is increased upon HCMV infection or reactivation." (PMID 33808294, 2021). "The association of persistent HCMV infection with vascular disease could also be partly explained by recruitment of activated T cells to peripheral sites of latency, as demonstrated here, as it is long established that CXCR3 expressing CD4+ T cells are recruited to atherosclerotic plaque sites." (PMID 33912186, 2021). "In the context of HCMV infection, we have previously demonstrated that secreted factors from latently infected CD34+ cells promoted the migration of CD14+ monocytes and resting CD4+ T cells." (PMID 33912186, 2021). "As is known, both CD4+ and CD8+ T cells play critical roles in the cell-mediated control of HCMV infection and clinical disease." (PMID 32025866, 2020). "This is also seen in primary HCMV infection, where development of the lymphoproliferative response to HCMV is delayed compared to the development of CD4+ and CD8+ IFN-γ-producing T cells." (PMID 32509591, 2020). "The aim of the work was to monitor the occurrence of persistent generalized lymphadenopathy, toxoplasmosis, and Cytomegalovirus infection in HIV-positive patients and analyze the clinical signs of the disease in relation to the number of CD4 T lymphocytes." (PMID 31690039, 2019). "This study followed the occurrence of PGL, toxoplasmosis, and Cytomegalovirus infection in 32 HIV-positive patients and analyzed the clinical signs of disease in relation to the number of CD4 T lymphocytes." (PMID 31690039, 2019). "IFN-γ produced by CD4+ T cells can block HCMV replication in vitro, highlighting the important role of IFN-γ in controlling HCMV infection." (PMID 29377960, 2018). "CD4+ and CD8+ T cell responses play a critical role in controlling CMV infection in both mouse and human." (PMID 28265272, 2017). "Although the CD4+ response was low, it still passed the threshold of 0.5% cytotoxic CD28−CD4+ T cells previously shown to be the minimal indication of hCMV infection." (PMID 28392788, 2017). "The impact of CMV infection resulted in increased numbers of differentiated CD8+ and CD4+ T cell populations, which has often been described; however, this phenomenon was irrespective of donor age in this cohort." (PMID 28647908, 2017). "CD4+CD28null T cells, however, are relatively increased in AAV and found to be related to the previous CMV infection." (PMID 28084533, 2017). "As hCMV infection is known to also induce the expansion of CD8+ and γδ+ effector T cells, we analyzed these T cell lineages in parallel to the CD4+ T cells." (PMID 28392788, 2017). "As expected, a high frequency of HCMV-reactive cells was detected in the memory CD4+ and CD8+ compartment at the early time point after primary HCMV infection." (PMID 29112951, 2017). "The aims of this study were to determine whether HCMV-specific CD4+ T cells secreting cIL-10 increase with age and long-term viral carriage and to determine whether there are changes in breadth and frequency of the IFNγ-secreting T cell response to HCMV infection in healthy older donors." (PMID 28694811, 2017). "Lower levels of naïve CD4+ T cells appear to be HCMV-seropositivity dependent rather than age related, suggesting differential effects of aging and HCMV infection on T cell subsets." (PMID 28082969, 2016).
HCMV infection (continued). "In chronic HCMV infection, a significant proportion of the CD8+ and CD4+ T cell pools recognise viral antigen." (PMID 27861512, 2016). "It is now well documented that both humoral and cellular (including CD4+ T cells and CD8+ T cells) immune responses play an important role in the control of HCMV infection and disease." (PMID 18806877, 2008). "The Swedish OCTO and NONA longitudinal immune studies found that inverted CD4+/CD8+ ratios (< 1) in the very elderly were significantly associated with increased 2‐year mortality and correlated with persistent cytomegalovirus infection." (PMID 41448851, 2025). "In fact, the CD4+ CFC-iDC showed a higher sensitivity in predicting self-resolving infection (Controller patients), while the CD4+ CFC-pp65 pool showed the best specificity in predicting Non-Controller patients that required treatment for an HCMV infection." (PMID 39195215, 2024). "Indeed, both CD4+ and CD8+ T cells were shown to play crucial roles in the resolution of acute CMV infection in adult mouse models." (PMID 34948284, 2021). "LN contained the highest numbers of CM and EM CD4+ and CD8+ T cells after HCMV infections." (PMID 30524448, 2018). "One important new finding observed in this model was that HCMV infections promoted also thymic development of CD4+ T cells and this was not lessened after viral reactivations." (PMID 30524448, 2018). "Consequently, the relative numbers of CD4+ T effector and memory cells that produce IFN-γ and IL-10 during the various phases of CMV infection likely form an axis that regulates the magnitude, duration, and reactivation of CMV in both mice and men." (PMID 28647908, 2017). "Interestingly, the Hobit+CD4+ T cell response demonstrated relative similar kinetics as the CD8+ and γδ+ T cell responses after resolution of primary hCMV infection, suggesting that antigenic stimulation also antagonizes Hobit expression in human T cells." (PMID 28392788, 2017). "CD4+CD28null T cells are increased in AAV and related to the previous CMV infection." (PMID 28084533, 2017). "While huNSG mice are useful to analyze HCMV infection, these mice are limited due to the lack of functional B-cells, CD4+ and CD8+ T-cells, dendritic cells, and limited reconstitution of endothelial and epithelial cells." (PMID 28428537, 2017). "Cytotoxic hCMV-specific CD4+ T cells also express CX3CR1, which may direct migration to inflamed endothelium, a major site of hCMV infection." (PMID 28392788, 2017). "In immunosuppressed patients, low CD4 T cell counts are correlated with EBV-related diseases; in renal transplant patients, CD4 T cells are critical for recovery of HCMV infection and in HIV patients low numbers of CD4 T cells are correlated with HCMV-associated diseases." (PMID 26599878, 2015). "It was found that both levels of total and HCMV-specific CD4+ T cells were significantly higher in patients with spontaneous control of HCMV infection as compared to non-protected patients." (PMID 25166270, 2014). "Notwithstanding the initial lack of specific CD4+ T-cells, also group 3 patients spontaneously controlled HCMV infection in the absence of antiviral therapy." (PMID 25166270, 2014). "Expansion of the CD4+ CD28− subset was particularly pronounced in HCMV positive RA patients, indicating that the disease per se is probably not the cause for the strong expansion of CD4+ CD28− cells, but the coincidence of disease and HCMV infection." (PMID 24967373, 2014). "In this study, we adopted a method enabling the simultaneous determination of both HCMV-specific CD4+ and CD8+ T cell responses, but it seems that measurement of HCMV-specific CD4+ T-cells alone might be sufficient to define protection from HCMV infection." (PMID 25166270, 2014).